SMYD3 (SET and MYND domain containing 3)
Diseases named in the same sentence as SMYD3 in open-access papers (continued):
Sharing a sentence is not in itself a finding about the gene and the disease.
tumor (68 papers, 2011 to 2025). "The clearance of tumor cells by phagocytes caused by SMYD3 knockdown was abolished by SREBP1 overexpression in ccRCC." (PMID 40548645, 2025). "Smyd3-Shcbp1 signaling shapes the tumor immunosuppressive microenvironment (TIME) and is associated with immune therapy resistance to PD1 antibody treatment." (PMID 40157910, 2025). "In prostate cancer, SMYD3 is frequently overexpressed and plays a critical role in regulating tumor-associated phenotypes through its methyltransferase activity." (PMID 39482529, 2024). "Consistent with the reduction in tumor size, SMYD3-deficient tumor tissues exhibited diminished proliferation (Ki67) and increased cell death (cleaved-Caspase-3), as revealed by immunohistochemical staining." (PMID 38191478, 2024). "Our results have demonstrated a role for the catalytic methyltransferase activity of SMYD3 in phenotypes linked to tumor development and progression of PCa." (PMID 37976356, 2023). "In these tumor types, SMYD3 overexpression has been implicated in promoting survival, migration, and invasion; therefore, it is critical to clearly identify the molecular oncogenic mechanisms reliant on SMYD3." (PMID 37976356, 2023). "In SMYD3-enriched subtypes, including classical, TP-53 mutation, smoking and alcohol consumption groups, patients tended to exhibit unfavourable tumor differentiation and prognosis." (PMID 37237385, 2023). "Our study assessed the role of SMYD3 in GC cell proliferation given that increased SMYD3 expression was associated with enlarged tumor sizes and advanced pT stage." (PMID 37386026, 2023). "We demonstrate that SMYD3 critically regulates tumor-associated phenotypes via its methyltransferase activity in PCa cells and mouse xenograft models." (PMID 37976356, 2023). "We found that SMYD3 deficiency significantly reduced the number of tumor nodules and HCC cell lung metastasis in vivo." (PMID 36575438, 2022). "We demonstrated that SMYD3 associated with the NuRD (MTA1/2) complex to repress the expression of some tumor suppressor genes." (PMID 36575438, 2022). "Clinically, positive SMYD3 expression was significantly associated with larger tumor size, increased lymph node metastasis, and advanced TNM stage." (PMID 33637115, 2021). "The authors further showed that preventing SMYD3 catalytic activity in mouse models with oncogenic RAS mutations inhibited tumor development." (PMID 33769711, 2021). "High SMYD3 expression was significantly associated with advanced tumor stage and was identified as an independent prognostic factor of poor survival in patients with CRC." (PMID 33637115, 2021). "In this light, our data suggest that YAP1 and GATA3 are important target genes for future analysis on the impact of SMYD3‐mediated regulation of tumor‐associated genes." (PMID 28781952, 2017). "Our data indicated that the expression of Smyd3 could be stimulated by ERα in synergy with the loss of Brca1 and enhance tumor outgrowth in nude mice with Brca1 mutant cells." (PMID 40157910, 2025). "We next assessed whether the decreased tumor growth and metastatic burden caused by repression of SMYD3 in the PC-3 xenografts could be rescued by expressing wild-type SMYD3 or the catalytically inactive F183A mutant." (PMID 37976356, 2023). "In addition, IHC staining revealed that low SMYD3 expression in xenograft tumor tissue was associated with weak PKM2 staining." (PMID 36057625, 2022). "Overexpression of SMYD3 is associated with tumor cell growth." (PMID 31737645, 2019). "SMYD3 mRNA and protein expression levels were significantly increased in GC tissues and cell lines relative to that in healthy tissues, with high SMYD3 expression being significantly associated with larger tumor size, lymph node metastasis, and later TNM staging." (PMID 36816359, 2023).
tumor (continued). "GO and KEGG analyses revealed that these DEGs (excluding SMYD3) were associated with the regulation of gene transcription, cell differentiation, cell proliferation regulation, stem cell differentiation, cell growth factors, and tumor-associated signalling pathways." (PMID 37237385, 2023). "We therefore focused on the functions of Smyd3 and Esr1 in gene expression, tumor initiation and progression." (PMID 40157910, 2025). "The animals were distributed into two experimental groups, which were treated for 7 days with the vehicle or with EM127 to assess the potential of SMYD3 inhibition to prevent tumor metastasis." (PMID 40588481, 2025). "Examination of tissue sections revealed significant tumor regression and reduction in Ki67 staining in samples derived from SMYD3-KO HCT-116-xenografted mice." (PMID 40588481, 2025). "To assess the impact of SMYD3 pharmacological inhibition on chemosensitivity in vivo, we monitored tumor growth in a xenograft mouse model." (PMID 40588481, 2025). "Tsai's study aimed to observe the immunomodulatory function of SMYD3 by administering anti‐sense oligonucleotides treatment in mice, which impacted the expression of SMYD3 in both tumor and immune cells." (PMID 40548645, 2025). "The results of this experiment revealed marked tumor regression, which was primarily characterized by the presence of fibrotic tissue tending to restrain neoplastic invasion in SMYD3-KO tumors compared to their WT SMYD3 counterpart." (PMID 40588481, 2025). "Ectopic expression of Cd47 effectively reversed Smyd3 knockdown‐mediated tumor growth inhibition in an orthotopic syngeneic mouse model." (PMID 40548645, 2025). "Genetic suppression of SMYD3 reduced metastatic potential and improved oxaliplatin response in vivo, while genetic or pharmacologic perturbation attenuated tumor–stroma crosstalk and enhanced oxaliplatin sensitivity in vitro." (PMID 41301830, 2025). "We also show that higher SMYD3 protein expression levels in human HPV-negative HNSCC tumors are associated with heavier smoking history and poor tumor grade." (PMID 39762343, 2025). "In order to explore the antitumor mechanism of ZYZ384, the inhibitory effect of ZYZ384 on SMYD3 was determined in tumor tissues." (PMID 39286779, 2024). "Overall, the data collected on tumor spheroids strongly support the efficacy of SMYD3 inhibition in increasing the cytotoxic effects of CHTs and therefore its potential as a therapeutic strategy to overcome chemoresistance." (PMID 38812026, 2024). "The clone numbers of metastatic tumor burden in the liver from the SMYD3 knockdown group were much lower compared with the control group, and the size of metastasis clone size showed a similar trend." (PMID 38191478, 2024). "In vivo, mouse models further validate the role of SMYD3 in reducing both tumor growth and metastasis." (PMID 38191478, 2024). "This analysis revealed significant tumor regression, which was mainly characterized by the presence of fibrotic tissue tending to restrain neoplasm invasion in SMYD3-KO tumors treated with irinotecan compared with those treated with the vehicle alone." (PMID 38812026, 2024). "The SMYD3 mRNA is highly expressed in multiple tumor types relative to normal tissue and frequently increases further in advanced disease stages." (PMID 37976356, 2023). "Together, our findings show that SMYD3 plays a critical role in tumor cell migration, invasion, anchorage-independent growth, as well as cell–extracellular matrix, cell-cell, and cell-fibroblast adhesion in PCa cells in vitro." (PMID 37976356, 2023). "This type of enzymatic histone alteration was augmented by tumor-specific proteolysis of the SMYD3 N-terminal 34 residues to release the methylated protein substrate." (PMID 36838987, 2023). "Tumor samples stratified by Gleason score also showed increased SMYD3 mRNA expression relative to normal tissue, with more SMYD3 mRNA present in higher-grade tumors." (PMID 37976356, 2023).
tumor (continued). "SET and MYND domain-containing protein 3 (SMYD3), a histone lysine methyltransferase, is implicated in gene transcription regulation and tumor development." (PMID 37237385, 2023). "New epigenetic mechanisms and a theoretical basis for intervention using anti-tumor drugs targeting SMYD3 in OSCC are presented." (PMID 37237385, 2023). "We next investigated the role of SMYD3 on tumor behavior in vivo by generating flank and orthotopic mouse xenografts of PC-3 Tet-on shSMYD3 cells." (PMID 37976356, 2023). "As previously observed, knockdown of SMYD3 in the xenografts resulted in significantly reduced tumor growth rate compared to untreated controls." (PMID 37976356, 2023). "It was revealed that SMYD3 was positively correlated with HMGA2 expression in most tumor and normal tissues and cell lines." (PMID 37237385, 2023). "Together, these data suggest that the catalytic activity of SMYD3 supports tumor growth and promotes metastatic spread in vivo." (PMID 37976356, 2023). "To date, few investigators have explored the function of SMYD3 in regulating the transcription of glycolysis-related genes in tumor cells, which was the novel aspect of our study." (PMID 36057625, 2022). "Based on our observations that SMYD3 and the NuRD (MTA1/MTA2) complex are physically and functionally associated, we next investigated if MTA1 or MTA2 have the same role of SMYD3 in tumor proliferation and invasion." (PMID 36575438, 2022). "In contrast, CP treatment of TKO;Smyd3-mutant mice triggered regression of disease with significantly reduced tumor volume, decrease in cell proliferation, and increase in cell apoptosis." (PMID 35819319, 2022). "In contrast, combined SMYD3 inhibition and CP therapy significantly restrained tumor progression for the full duration of the treatment protocol, well after other treatment conditions had failed." (PMID 35819319, 2022). "SMYD3 promotes tumour cell migration and invasion by strengthening epithelial-mesenchymal cells and enhancing telomerase activity during the cell cycle." (PMID 35610596, 2022). "We noted that the ablation and inhibition of SMYD3 in SCLC cells partially delayed tumor growth, whereas additional CP treatment significantly halted tumor growth or caused some tumors to regress in size." (PMID 35819319, 2022). "The average tumor weight/volume of mice in the SMYD3 interference group was 46.4%/44.9% of that in the control group." (PMID 36575438, 2022). "A growing body of evidence indicates that SMYD3 is overexpressed in several human tumors, highlighting its crucial role in carcinogenesis and tumor progression." (PMID 35495117, 2022). "Other expressed transcripts encrypting histone methyltransferases are involved in tumor proliferation, particularly histone-lysine N-methyltransferase (SMYD3)." (PMID 33557100, 2021). "Results demonstrated that tumor tissues had significantly lower SMYD3 promoter methylation levels than adjacent normal tissues." (PMID 33637115, 2021). "In contrast, SMYD3 knockdown significantly suppressed tumor growth and reduced tumor proliferation; these effects were largely reversed by S1PR1 overexpression." (PMID 34301921, 2021). "Downregulation of SMYD3 expression significantly reduces the ability of tumor cells to expand and migrate in vitro." (PMID 34335697, 2021). "Knocking out SMYD3 dramatically reduced the tumor formation capacity induced by these carcinogens, as shown by a decrease in the number and size of tumor foci in the colon and liver compared to wild-type mice." (PMID 34503239, 2021). "Kaplan–Meier analysis demonstrated that patients with high tumor levels of SMYD3 mRNA had poorer overall survival." (PMID 33637115, 2021). "In ovarian cancer, SMYD3 regulates tumor proliferation and apoptosis by downregulating CDKN2A through tri-methylation of H4K20 and upregulating BIRC3 through tri-methylation of H3K4." (PMID 34201935, 2021).
tumor (continued). "In colorectal cancer and LIHC, SMYD3 can activate multiple signal pathways by regulating transcription, and promote, among other malignant cell phenotypes, tumor cell proliferation, invasion, and epithelial to mesenchymal cell transformation." (PMID 34335697, 2021). "They identified that SMYD3 expression positively correlated with tumor size, TNM stage, perineural invasion, and lymph node metastasis in pancreatic adenocarcinoma." (PMID 33637115, 2021). "In vivo experiments demonstrated decreased tumor growth, decreased cell proliferation, and increased apoptosis in SMYD3-depleted mice." (PMID 33637115, 2021). "In pancreatic adenocarcinoma, high SMYD3 levels positively correlated with tumor size, TNM stage, perineural invasion, lymph node metastasis and shorter survival." (PMID 34503239, 2021). "SMYD3, termed SET and MYND domain-containing protein 3 as well, is methyltransferase overexpressed in humanized tumor cells." (PMID 33322383, 2020). "In vitro, SMYD3 depletion leads to decreased anchorage independent growth, and xenografts formed by SMYD3-depleted tumor cells results in smaller tumor nodules." (PMID 31935919, 2020). "A more comprehensive understanding of the different mechanisms leading to SMYD3 upregulation is warranted, to define tumor-specific mechanisms resulting in SMYD3 over-expression." (PMID 31935919, 2020). "Expression of SMYD3 mRNA in tumor tissues was significantly higher than that in adjacent non-tumor tissues (P = 0.008)." (PMID 32071406, 2020). "SMYD3 serum levels were measured in 293 patients and SMYD3 mRNA expression was quantified in 48 pairs of hepatocellular tumor and adjacent non-tumor liver tissues." (PMID 32071406, 2020). "Of note, genetic depletion of SMYD3 interferes with the activation of proliferative signals and inhibits colony formation, cell migration, invasion and xenograft tumor formation." (PMID 31935919, 2020). "In HCC, SMYD3 positive expression is significantly linked to hepatitis B virus (HBV) infection, microvascular invasion, poor tumor differentiation, high TNM stage, and a worse prognosis, suggesting that SMYD3 plays an important role in HCC progression." (PMID 31935919, 2020). "Depletion of SMYD3 inhibited BC cell proliferation, colony formation, migration, invasion, and xenograft tumor growth." (PMID 32007952, 2020). "SMYD3 mRNA expression was upregulated in HCC tumor compared to adjacent non-tumor tissues, providing further evidence of a role of SMYD3 in HCC development." (PMID 32071406, 2020). "Current research of SMYD3 focuses primarily on its roles in tumor cell growth and muscle development." (PMID 31737645, 2019). "Then we used western blot to compare protein expression of SMYD3 and its downstream regulators in tumor tissues of both groups." (PMID 31417652, 2019). "50% of mice in SMYD3 knockdown group formed tumor (3/6) and all the mice in vector control group formed tumor (6/6)." (PMID 31417652, 2019). "We also use nude mice subcutaneous tumor model and patient-derived xenograft (PDX) model to investigate the tumor promotive function of SMYD3 in vivo." (PMID 31417652, 2019). "SMYD3 positive expression in HCC was significantly associated with HBV infection, microvascular invasion, poor tumor differentiation, and high TNM stage." (PMID 30646949, 2019). "Overexpression of SMYD3 often correlates with poor prognosis and its knockdown inhibits tumor growth." (PMID 28050603, 2017). "Through these methylations, SMYD3 is involved in tumor cell viability, adhesion, migration and invasion." (PMID 28050603, 2017). "H4K5 methylation by SMYD3 provides a potential new link between chromatin dynamics and neoplastic disease." (PMID 28050603, 2017). "SMYD3 interacts with PC4 in tumor cells and such interaction stimulates oncogenic gene expression through deposition of H3K4 tri-methylation." (PMID 28050603, 2017). "We extended the studies to investigate nuclear expression of active Src, HMGA2, and SMYD3 expression in human PDAC tumor samples." (PMID 26695438, 2016).
tumor (continued). "The CAM assay was performed to evaluate the effect of SMYD3 on tumor growth and angiogenesis in vivo." (PMID 25980436, 2015). "Interestingly, higher SMYD3 protein levels were associated with higher Gleason score suggesting that this alteration might be associated with increased tumor aggressiveness, in line with previous observations and providing further support for an oncogenic role in PCa." (PMID 25980436, 2015). "We silenced SMYD3 and assess its impact through in vitro (cell viability, cell cycle, apoptosis, migration, invasion assays) and in vivo (tumor formation, angiogenesis)." (PMID 25980436, 2015). "A number of histone methyltransferases, including Setd3, Setd5, Suv39h2, Smyd3, Prmt3, Prmt6, Nsd1, and Nsd2, were up-regulated in metastases compared to disseminated tumor cells or primary tumors." (PMID 23520493, 2013). "Reducing the levels of SMYD3 by SMYD3 intronic RNA, resulted in reduced tumor growth, and revealed SMYD3 intronic RNA to harbor tumor suppressive abilities." (PMID 24216986, 2013). "The positive correlation was also observed between the expression of Smyd3 and Shcbp1 in premalignant virgin MG, P12 mammary and tumor tissues at both protein and mRNA levels, indicating Shcbp1 might mediate Smyd3 signaling." (PMID 40157910, 2025). "T-cell proliferation was recovered when T cells were cocultured with MDSCs from tumors expressing either sgSmyd3 or OE-Smyd3/sgShcbp1, demonstrating the strong inhibition of T cell proliferation by MDSCs in tumor tissues with elevated Smyd3-Shcbp1 oncogenic signaling." (PMID 40157910, 2025). "Altogether, these findings showed that elevated ERα signaling could enhance Smyd3 expression and cell proliferation in vitro and tumor growth in pregnant mice with G600 Brca1 mutant cells." (PMID 40157910, 2025). "Trametinib, a potent inhibitor of MEK/MAPK, could reverse the expression of Smyd3 and Shcbp1 in both Brca1 mutant and WT tumor bearing mice." (PMID 40157910, 2025). "Similarly, our preclinical model suggests that the alternative approach of targeting SMYD3 to affect CD47 signaling combined with a PD‐1 inhibitor results in increased tumor suppression in ccRCC." (PMID 40548645, 2025). "Collectively, these data show that therapeutic blockade of the SMYD3/CDCP1 axis disables tumor-promoting CAF activation, restrains hepatic metastatic outgrowth, and sensitizes CRC to oxaliplatin, supporting this axis as a tractable target to improve chemotherapy response." (PMID 41301830, 2025). "Given that the disruption of either Smyd3 or Shcbp1 could inhibit the tumor outgrowth, we hypothesized that SMYD3-SHCBP1 signaling might shape TIME benefiting tumor growth." (PMID 40157910, 2025). "We then used a semi-in vivo 3-dimentional tumor slice culture (3D-TLC) platform to examine whether BCI-121 could inhibit Smyd3 action in tumor tissue sections." (PMID 40157910, 2025). "Finally, our study also uncovered therapeutic options for suppressing tumor formation by suppressing Smyd3-Shcbp1 signaling using a combination of trametinib and αPD1 treatment." (PMID 40157910, 2025). "To further confirm whether the inhibitory effect is indeed due to the inhibition of Smyd3 or Shcbp1, we orthotopically implanted G600 cells stably expressing either sgSmyd3 or sgShcbp1 into the fat pad of nude mice and monitored tumor growth." (PMID 40157910, 2025). "Moreover, we identified CD47, an innate immune checkpoint molecule expressed on tumor cells, as the downstream molecule of SMYD3 that inhibits anti‐tumor immunity in ccRCC." (PMID 40548645, 2025). "In support of this notion, elevated protein levels of Smyd3, H3K4me3, and Shcbp1, and p-Mek, and p-Erk and Kras were detected in tumor tissues with OE-Smyd3, but these protein levels were significantly decreased in tumor tissues expressing sgSmyd3 or OE-Smyd3/sgShcbp1." (PMID 40157910, 2025).